MIR3119-2 (microRNA 3119-2)
Synonyms: hsa-mir-3119-2
Gene: MicroRNA gene on chromosome 1 (170,151,378 to 170,151,462, forward strand). Ensembl gene ENSG00000263390.
Homologues: Orthologues: chimpanzee MIR3119-2 (100% identical).